CPT1A (carnitine palmitoyltransferase 1A)
Diseases named in the same sentence as CPT1A in open-access papers (continued):
Sharing a sentence is not in itself a finding about the gene and the disease.
hepatocellular carcinoma (23 papers, 2011 to 2026). A malignant tumor that arises from hepatocytes. "In hepatocellular carcinoma (LIHC_GSE166635), 11 cell populations were detected, with CPT1A expression enriched in endothelial, malignant, and mast cells." (PMID 41219902, 2025). "In hepatocellular carcinoma, PPARγ-specific activation of RNF5 facilitates K63-linked ubiquitination of IGF2BP1, increasing CPT1A expression and accelerating tumor progression." (PMID 41219902, 2025). "In hepatocellular carcinoma (HepG2 cells), miR-370 directly downregulates CPT1A expression at the transcriptional level, reducing FAO rates and promoting lipid accumulation." (PMID 41219902, 2025). "T3 decreased fatty acid synthase (FAS), sterol regulatory element-binding protein (SREBP), stearoyl-coenzyme A desaturase 1 (SCD1), and elevating carnitine palmitoyltransferase 1A (CPT1A) gene expression in mouse hepatocellular carcinoma (Hepa 1-6) cells." (PMID 31963885, 2020). "For example, it has been shown that CPT1A-dependent FAO is required for the maintenance of tumor initiation cells in hepatocellular carcinoma as well as normal hematopoietic and neural stem cells." (PMID 32913185, 2020). "This approach may allow selective targeting of CPT1A-rich hepatocellular carcinoma cells or CPT1B-rich cardiomyocytes while minimizing off-target toxicity." (PMID 41219902, 2025). "PTE (10 μg/mL) and GHG (10 μg/mL) also enhanced protein expression of CPT1A in HepG2 hepatoma." (PMID 26199579, 2015). "Another CPT1A inhibitor, Perhexiline, showed promising antitumour effects in hepatocellular carcinoma (HCC) cells." (PMID 38610991, 2024). "Furthermore, hypoxia-induced lipid droplet accumulation is accompanied by the inhibition of fatty acid β-oxidation though HIF-1 and HIF-2-dependent downregulation of PGC-1α and carnitine palmitoyltransferase 1A (CPT1A) in both hepatoma and renal cell carcinoma cells." (PMID 32389123, 2020). "During glucose deficiency, phosphorylation of ACC1 leads to dissociation of the ACC1-CPT1A complex and mitochondria localization of CPT1A, thus promoting FAO-mediated hepatocellular carcinoma cell aggressive phenotype." (PMID 28399876, 2017). "As a reversible inhibitor that targets both CPT1A and CPT1B, perhexiline maintains anti-cancer efficacy while demonstrating reduced cardiotoxicity in preclinical chronic lymphocytic leukemia (CLL) and hepatocellular carcinoma (HCC)." (PMID 40867868, 2025). "In addition, evidence has been presented showing that CPT1A is regulated as a transcriptional target gene by the p38 MAPK signaling pathway and affects the proliferation of hepatocellular carcinoma cells." (PMID 37686221, 2023). "Notwithstanding, CPT1A mRNA was induced in expression (panel A1-A3) in PHHs and hepatoma cell lines after lipid but not the combined lipid and TNFα treatment." (PMID 30547786, 2018). "In our in vitro experiments using HepG2, EGCG did not enhance CPT1A expression in cultured hepatoma." (PMID 26199579, 2015). "We assessed the expression of PPARα mRNA in human hepatocellular carcinoma tissue and non-cancerous tissue, as well as the expression of target genes of PPARα, carnitine palmitoyltransferase 1A and cyclin D1 mRNAs." (PMID 22168458, 2011).
melanoma (22 papers, 2018 to 2026). A malignant, usually aggressive tumor composed of atypical, neoplastic melanocytes. "In melanoma, viral infection of mitochondria can induce epigenetic perturbations that upregulate CPT1A expression, enhance mitochondrial antiviral signaling protein palmitoylation, and intensify interferon-I responses." (PMID 41219902, 2025). "For instance, in melanoma, CPT1A-mediated succinylation of PD-L1 accelerates its degradation via the lysosomal pathway, enhancing T-cell cytotoxicity and response to anti-PD-1 therapy." (PMID 41383634, 2025). "While glycolysis is inhibited, melanoma cells can use CPT1A to drive mitochondrial FAO to maintain their viability." (PMID 37563469, 2023). "Previous studies have shown that melanoma cells increase CPT1a-dependent fatty acid oxidation in response to treatment with MAPKi therapy, and inhibiting MAPK, glycolysis, and fatty acid oxidation together inhibits tumor cell growth in vitro and in vivo." (PMID 35565240, 2022). "In melanoma, DCs—through the wnt5a-β-catenin-PPARg signaling pathway—can upregulate the expression of FA transport protein carnitine palmitoyl transferase-1a (CPT1A), driving the FAO process and protumor effects." (PMID 35406621, 2022). "In melanoma, tumor cells activate WNT5a/β-catenin-PPARγ signaling, which in turn upregulates the expression of carnitine palmitoyltransferase-1a (CPT1A) to promote FAO." (PMID 36244976, 2022). "Melanomas use Wnt5α to upregulate lipid uptake and carnitine palmitoyltransferase-1A (CPT1A) in DCs, driving fatty acid oxidation and oxidative phosphorylation, leading to the establishment of a site with immune privilege." (PMID 33670082, 2021). "The tumor-derived Wnt5 ligand can activate β-catenin signaling in TADC, which upregulates PPARγ to induce Carnitine Palmitoyltransferase 1A (CPT1A)-driven FAO in a murine melanoma model." (PMID 34988072, 2021). "Particularly, the pharmacological blockade of CPT1A (the rate-limiting step for fat oxidation) reactivated glycolysis in MAPKi-treated melanoma cells." (PMID 32411231, 2020). "Similarly, inhibition of FAO through CPT1A antagonists (e.g., etomoxir) impairs ATP generation and redox buffering in drug-resistant melanoma cells." (PMID 41596686, 2026). "The expression of the genes encoding the key enzymes CPT1A and CPT2 is increased in melanoma." (PMID 41596686, 2026). "Importantly, CPT1A is a potential therapeutic target in melanoma, with its knockdown shown to inhibit the proliferation of V600E melanoma cells." (PMID 39367275, 2024). "Since downregulation of PPARα significantly suppresses CPT1A expression and subsequently suppresses FAO in melanoma cells, the hypothesis that activation of PPARα by WY-14,643 might affect CPT1A was raised." (PMID 36384580, 2022). "Thus, the concomitant inhibition of CPT1A, glycolysis, and MAPK synergistically inhibited tumour cell growth in vitro and in BRAFV600E-mutated melanoma mouse models." (PMID 32411231, 2020). "Furthermore, the irreversible inhibition of the fatty acyl chain transfer to the intermembrane space of the mitochondria (CPT1a) with etomoxir, or CPT1a lentiviral knockdown targeting both isoforms of CPT1a in YA-melanoma significantly reduced melanoma proliferation, OXPHOS, and ATP production." (PMID 40280124, 2025). "In experimental mouse models of melanoma metastasis, the inhibition of de novo FA synthesis with Orlistat or thiazolidinediones, or by inhibiting mitochondrial FA β-oxidation with drugs such as etomoxir, a carnitine palmitoyltransferase 1A (CPT1) inhibitor, had anti-tumour effects." (PMID 29739810, 2018). "Furthermore, young-MFP-melanomas expressed higher levels of FABP4, CPT1a, and CD36 than aged-MFP-melanomas validating that the young-MFP is an environment that enhances lipid metabolism in melanoma cells." (PMID 40280124, 2025).
melanoma (continued). "Additionally, inhibiting CPT1A, a key enzyme in FAO, improves antigen-specific CD8+ T-cell responses and dendritic cell (DC)-mediated T-cell priming, enhancing anti-PD-1 therapy in BRAFV600E melanoma." (PMID 39456967, 2024).
lung carcinoma (21 papers, 2017 to 2025). "In lung cancer, CPT1A deficiency weakens the immunosuppressive function of myeloid-derived suppressor cells in the TME while enhancing tumor cell ferroptosis." (PMID 41219902, 2025). "Further investigations have found a strong association with the c-Myc oncogene in lung cancer, demonstrating that CPT1A indirectly regulates c-Myc expression." (PMID 41339932, 2025). "Moreover, CPT1A is upregulated in patients with lung cancer, and high expression of CPT1A is associated with shorter OS, indicating a poor prognosis." (PMID 40016582, 2025). "Correlation analysis revealed that miR-365-3p was negatively correlated with CPT1A in the samples of patients with lung cancer, highlighting a clear and consistent pattern across all collected samples." (PMID 40016582, 2025). "By modulating fatty acid metabolism in lung cancer via the CPT1A-mediated FAO pathway, miR-365-3p plays a critical role in inhibiting the proliferation and migration of cancer cells, both in vivo and in vitro." (PMID 40016582, 2025). "In patients with lung cancer, miR-365-3p expression is negatively correlated with CPT1A expression, and both miR-365-3p and CPT1A expression levels predict good and poor clinical outcomes, respectively." (PMID 40016582, 2025). "Consistent with this, CPT1A levels were elevated in the residual tumor tissues from lung cancer patients after osimertinib treatment." (PMID 40479551, 2025). "We demonstrated that miR-365-3p not only inhibits FAO in lung cancer, but also decreases lung tumor growth by suppressing CPT1A-mediated FAO." (PMID 40016582, 2025). "Given that CPT1A involvement in tumor progression has been established, our study aimed to explore the function of the miR-365-3p/CPT1A axis in influencing lung cancer cell behavior, with a particular focus on cell proliferation and migration capabilities." (PMID 40016582, 2025). "Since c-Myc has been found to regulate NRF2/GPX4 cellular system, the CPT1A indirectly gives a contribution to suppressing ferroptosis in lung cancer." (PMID 41339932, 2025). "In our study, we demonstrate that miR-365-3p inhibits CPT1A expression by targeting its 3’-untranslated region in lung cancer cells." (PMID 40016582, 2025). "In summary, the miR-365-3p/CPT1A axis has substantial clinical significance and offer insights into the potential molecular mechanisms driving lung cancer progression and patient survival outcomes." (PMID 40016582, 2025). "In conclusion, this is the first study to demonstrate the biological function of the miR-365-3p/CPT1A axis in lung cancer." (PMID 40016582, 2025). "Consistent with our preliminary observations in 293T cells, the miR-365-3p mimics inhibited CPT1A expression in A549 and H1299 lung cancer cells." (PMID 40016582, 2025). "Cell proliferation assays revealed that both miR-365-3p mimics and CPT1A knockdown significantly reduced the proliferation rates of A549 and H1299 lung cancer cells." (PMID 40016582, 2025). "Building on our initial assessment of miR-365-3p and CPT1A expression levels in lung cancer and adjacent normal tissues, we further investigated the relation within lung cancer." (PMID 40016582, 2025). "Transfer RNA-derived fragment-16 suppresses lung cancer progression by impairing IGF2BP1 binding to CPT1A via N6-methyladenosine modification, thereby destabilizing CPT1A transcripts." (PMID 41219902, 2025). "Collectively, these findings underscore the critical role of the miR-365-3p/CPT1A axis in modulating lung cancer cell proliferation and migration." (PMID 40016582, 2025). "Immunofluorescence staining revealed that both miR-365-3p mimics and CPT1A knockdown led to a noticeable increase in the quantity of the lipid droplets present in lung cancer cells." (PMID 40016582, 2025).
lung carcinoma (continued). "L-carnitine produced by tumor-associated macrophages (TAMs) activates CPT1A and c-Myc, upregulates NRF2/GPX4 expression, augments antioxidant capacity, and downregulates ACSL4 expression, thereby suppressing ferroptosis in lung cancer cells." (PMID 41219902, 2025). "Remarkably, we found that in contrast to adjacent tissues and normal lung epithelial cells, lung cancer tissues and cells expressed higher CPT1A mRNA." (PMID 39679845, 2024). "A study shows that CPT1A significantly affects ferroptosis resistance in lung cancer stem cells and drives complex metabolic reprogramming." (PMID 39744129, 2024). "These aggregated N2-neutrophils secrete miR-4466, which promotes the BM of metastatic lung cancer cells through the SKI/SOX2/CPT1A axis." (PMID 39364322, 2024). "This study showed that tRF‐16 can decrease IGF2BP1's ability to bind to CPT1A and decrease CPT1A's stability, which can impact lung cancer cells' fatty acid metabolism and promote both in vivo and in vitro growth." (PMID 39679845, 2024). "Chemical inhibition of carnitine palmitoyltransferase 1A (CPT1A) by Etomoxir can significantly enhance radiosensitivity by downregulating the DNA repair pathways promoting the survival of lung cancer cells exposed to the ionized radiation." (PMID 35216362, 2022). "Furthermore, the disruption of fatty acid oxidation attenuates the ability of the miR-365-3p/CPT1A axis to modulate lung cancer cell proliferation and migration both in vitro and in vivo." (PMID 40016582, 2025). "As CPT1A plays a critical role in FAO, we explored the hypothesis that miR-365-3p influences FAO in lung cancer cells by modulating CPT1A activity." (PMID 40016582, 2025). "Our findings support the hypothesis that miR-365-3p exerts its effects on lung cancer cell metabolism primarily through the repression of CPT1A expression, leading to diminished FAO and consequent alterations in energy production." (PMID 40016582, 2025). "However, research elucidating the relationship between CPT1A and ferroptosis is still limited, and its relationship has been found in a certain cancer type, lung cancer." (PMID 40867868, 2025). "Collectively, our findings shed light on the function and mechanistic pathway of the miR-365-3p/CPT1A axis in lung cancer, which might provide a potential therapeutic target for lung cancer." (PMID 40016582, 2025). "In the present study, we revealed for the first time the function of CPT1A in lung cancer." (PMID 40016582, 2025). "Another study found that CPT1A inhibits the proliferation and migration of lung cancer cells." (PMID 38238472, 2024). "Additionally, a new feedback regulatory mechanism between CPT1A and c-Myc in the ferroptosis process of lung cancer stem cells was discovered, revealing how metabolic rewiring supports tumor cell survival during immune clearance." (PMID 39744129, 2024). "Interestingly, a recent report showed that the blockade of CPT1A by etomoxir promoted ferroptosis inducer erastin-induced lung cancer cell actual ferroptotic death via the GPX4 pathway." (PMID 39596904, 2024). "Accordingly, etomoxir significantly decreased the oxygen consumption rate and the DNA repair capability of lung cancer cells resistant to radiotherapy and restored their radiosensitivity, suggesting CPT1A as a potential target for the treatment of radiation-resistant lung cancer." (PMID 35159223, 2022). "However, the role of CPT1A in lung cancer and the regulatory mechanisms of microRNAs on CPT1A-mediated fatty acid oxidation remain largely unknown." (PMID 40016582, 2025). "ATP production assays indicated that the presence of miR-365-3p mimics or CPT1A knockdown led to a noticeable decrease in ATP production within lung cancer cells, reinforcing the notion that miR-365-3p regulation of CPT1A has a profound effect on the metabolic processes within lung cancer cells." (PMID 40016582, 2025). "However, the miRNAs that target CPT1A to regulate CPT1A-mediated FAO in lung cancer remains unknown." (PMID 40016582, 2025).
lung carcinoma (continued). "Thus, the miR-365-3p/CPT1A axis may be a promising therapeutic target in lung cancer." (PMID 40016582, 2025). "Thus, the miR-365-3p/CPT1A regulatory axis may be a potential therapeutic target for lung cancer." (PMID 40016582, 2025). "As an important rate‐limiting enzyme in fatty acid oxidation, CPT1A was reported to stabilize c‐Myc and activate the NRF2/GPX4 system to suppress ferroptosis and improve the efficacy of immunotherapy in lung cancer cells." (PMID 39811936, 2025). "Recent studies have shown that TAM interacts with carnitine palmitoyltransferase 1A (CPT1A), increasing resistance to iron death and inactivation of CD8 T cells in lung cancer." (PMID 39391313, 2024). "Studies on lung cancer cells have shown that MAPK1 phosphorylation inhibits FASN expression, while MAPK1 activation enhances the expression of fatty acid metabolism genes such as CPT1a in diabetic cardiomyopathy." (PMID 41010281, 2025). "Furthermore, miR-365-3p regulates CPT1A-mediated FAO and decreases the proliferation and migration of lung cancer cells." (PMID 40016582, 2025). "Additionally, there exists a negative correlation between miR-365-3p and CPT1A expression, and both are predictive of clinical outcome in lung cancer patients." (PMID 40016582, 2025).
leukemia (16 papers, 2013 to 2025). A malignant (clonal) hematologic disorder, involving hematopoietic stem cells and characterized by the presence of primitive or atypical myeloid or lymphoid cells in the bone marrow and the blood. "The inhibition of CPT1a caused cell growth arrest and induction of apoptosis along with mitochondrial damage in leukemia cells." (PMID 37256177, 2023). "The overexpression of CPT1A is often associated with tumor progression in several cancers such as breast, gastric, prostate, lymphoma, leukemia, ovarian, lung, and myeloma." (PMID 29445084, 2018). "CPT1A has a significant role in mitochondrial fatty acid synthesis, and its expression is associated with increased cell proliferation and suppression of apoptosis in various cancers, including leukemia." (PMID 39703843, 2024). "Targeting CPT1A in leukemia cell lines leads to a decrease in cancer cell proliferation and a reduction in apoptosis." (PMID 39703843, 2024). "The inhibition of CPT1A and associated FAO in leukemia cells by etomoxir or ranolazine augmented the efficacy of ABT-737-mediated cell death through pro-apoptotic Bak protein." (PMID 37256177, 2023). "A novel CPT1a inhibitor ST1326 has been proved effective on leukemia cell lines and primary cells obtained from patients with hematologic malignancies." (PMID 33926484, 2021). "Targeting CPT1a has shown remarkable anti-leukemia activity: A novel CPT1a inhibitor ST1326 has been proved effective on leukemia cell lines and primary cells obtained from patients with hematologic malignancies." (PMID 33926484, 2021). "Subsequent studies confirmed that the small molecule inhibitor of CPT1A can reduce fatty acid oxidation in tumor cells of leukemia and exert an anticancer effect by inhibiting cell proliferation and inducing apoptosis." (PMID 33381539, 2020). "We then treated leukemia cells with etomoxir, which inhibits CPT1A enzymatic activity." (PMID 40801789, 2025). "Previous studies showed the importance of FAO in apoptosis resistance by inhibition of Cpt1a with etomoxir in leukemia and endothelial cells; however, the mechanism by which etomoxir induced apoptosis, other than shifting cellular metabolism to glycolysis, was not determined." (PMID 34413485, 2022). "Exploiting this dependency, they demonstrated that inhibition of carnitine palmitoyl transferase 1A (CPT1A) could sensitize leukemia cells to the BH3-mimetic ABT-747." (PMID 32226926, 2020). "Moreover, the leukemia cells were chemosensitized by a CPT1a inhibitor." (PMID 37256177, 2023). "However, there is not yet a study to exclusively evaluate the prognostic value of CPT1a expression and possible combinational strategy with CPT1a inhibitor on AML.A majority of leukemia cells have a survival advantage over normal cells because they fail to undergo apoptosis." (PMID 33926484, 2021). "One CPT1A inhibitor, (R)-N-(tetradecyl carbamoyl)-amino carnitine (ST1326), inhibits the occurrence of lymphoma and leukemia." (PMID 37256177, 2023). "Etomoxir, an inhibitor of the carnitine-dependent transporter CPT1 (also known as CPT1A) and FAO, was able to eradicate ∼50% of quiescent leukaemia SCs in primary human myeloid leukaemia samples, and sensitize leukaemia cells to apoptosis-inducing agents in a murine model." (PMID 29991569, 2018).